RB1 (RB transcriptional corepressor 1)
Diseases named in the same sentence as RB1 in open-access papers (continued):
Sharing a sentence is not in itself a finding about the gene and the disease.
tumor (continued). "Pull-down using an E2F1 antibody showed enrichment of E2F1 at a consensus-binding site within the Hells promoter in samples that highly express HELLS protein: P0 wild-type and P21 Rb1/p107 DKO retinae and human tumor cells, but not in P21 Cre-negative Rb1/p107." (PMID 32071286, 2020). "This analysis highlights the predominant contribution of copy number alterations and identifies a critical role for disruptive structural variants in the inactivation of clinically important tumour suppressor genes, including PTEN and RB1, which are not currently captured by diagnostic assays." (PMID 33144218, 2020). "For instance, recent pre-clinical studies in pancreatic adenocarcinoma suggest that CDK4/6 inhibitors should be administered after (not before) cytotoxic chemotherapeutics since activation of RB1 represses the DNA repair machinery and enhances DNA damage-induced tumor cell death." (PMID 32344731, 2020). "Thus, it was shown that therapies aiming to reactivate the RB pathway may have tumor suppressive effects, not through a suppression of cell proliferation, but inducing the reversion of cell state changes associated with advanced tumor progression and related to RB1 deficiency." (PMID 31366128, 2019). "Given that RB1, but not p107 or p130, is a bona fide tumor suppressor, we tested the hypothesis that the unique p16 upregulation after RB1 loss functioned to regulate epithelial cell growth and protect against carcinogenesis." (PMID 28414317, 2017). "In addition, MEG3 may activate RB1 directly by RNA–protein interactions or indirectly by activating CDKN4A, which in turn activates the RB1 to suppress cell proliferation and tumor formation." (PMID 29069869, 2017). "Thus, the current genetically engineered mice represent a tractable model to identify these critical p16 tumor suppressive functions that are not mediated through RB1." (PMID 28414317, 2017). "Interestingly, in U87 cell lines lacking the expression of PTEN, miR-26a-5p was still capable of inhibiting tumor growth, and the overexpression of PTEN or RB1 could both antagonize the proliferative effects of miR-26a-5p." (PMID 26439688, 2015). "To better understand the importance of RB1 activity in HPV-negative SCCHN, we investigated the prognostic value of inhibitory CDK4/6 phosphorylation of RB1 on threonine 356 (T356) in archival HPV-negative tumor specimens from patients who underwent surgical resection and adjuvant radiation." (PMID 26265441, 2015). "RB1 underexpression is associated with nonresponse to BCG +IFN-α treatment and tumor recurrence." (PMID 26160835, 2015). "However, the other tumor suppressor RB1 demonstrated no change in tumor tissue of the Cs+NDMA group (P = 0.440)." (PMID 26313366, 2015). "Additionally, they found RB1 promoter hypermethylation in all tumor samples, irrespective of MCPyV status and RB1 expression." (PMID 25329450, 2014). "Whether or not PNS, Rg1, Rb1 or R1 exert anti-angiogenesis effects in the context of tumor growth and progression remains to be evaluated." (PMID 24903055, 2014). "However, the contribution of different aspects of pRB function to its tumor suppressive role is not clear as complete deletion of the Rb1 gene has many consequences." (PMID 23936539, 2013).
tumor (continued). "Given the high predictive accuracy and quantitative nature of the CCND1/CDKN2A expression assay, the assay could be utilized to stratify patients for anti-tumor agents with preferential effects on either RB1-positive or -negative tumors." (PMID 21447152, 2011). "This also makes it difficult to establish a threshold to distinguish RB-positive and -negative tumors that would guide investigators to determine whether the tumors be treated with anti-tumor agents whose effects are dependent on RB1 status." (PMID 21447152, 2011). "Since tumor material was not available, peripheral assessment of methylation of the RB1 promoter in leukocytes would not have been informative because the dynamics of DNA methylation in primary tumor tissues are clearly different from normal cells, and not confined to specific CpG sites." (PMID 19640284, 2009). "Nonetheless, the finding of tumours displaying LOH at the RB1 locus without any abnormality in the remaining RB1 allele, but with the absence of pRB expression, supports the existence of mutations in regions such as promoter or introns, which are frequently not explored or escape SSCP studies." (PMID 12556968, 2003). "However, the fascinating observation of our study is that the hub genes including CDK1, CDK2, CCNB1, and HDAC1 and common genes including E2F3 identified in Rb tissues are well-known oncogenes that trigger cell cycle progression in tumor cells in the absence of RB1 gene." (PMID 35359459, 2022). "The MYCN-amplified RB1-proficient hypermethylation-driven, differentially expressed genes are a functionally diverse set of genes, suggesting that hypermethylation in this tumor subtype is indeed not functionally unidirectional, and it may be modulating multiple aspects of the tumor biology." (PMID 36245757, 2022). "We hypothesized that the lack of RB1 in Rb tumor cells mediates enhancement of glycolysis independent energy production, primarily via enhanced mitochondrial function; therefore, Rb tumor cells possibly switch to alternate fuels and energy production mechanisms such as mitochondrial fat oxidation." (PMID 36291051, 2022). "However, despite the increased resolution of WGS, with such complicated rearrangement patterns, it was not possible to confirm whether both copies of RB1 were affected by the rearrangements in some tumours." (PMID 33670346, 2021). "Only one variant in the RB1 and one in the MSH6 genes identified in tissue specimens at low frequency (<5%) were not identified in liquid biopsy samples, and, interestingly one SNV in MTOR gene was identified in liquid biopsy and not in the matched tumor tissue sample." (PMID 34441402, 2021).
tumor (continued). "A molecular testing panel of the tumor tissue showed the presence of 21 mutations (none of them treatable), including MDM2 (murine double minute 2), KRAS (Kirsten rat sarcoma) amplification, RB1 (retinoblastoma protein) amplification, and STK11 (serine/threonine kinase 11)." (PMID 34298855, 2021). "To directly test whether Rb loss in a breast epithelial cell could cause synthetic lethality with SKP2 inhibition, we silenced SKP2 using two different siRNAs in non-tumour breast epithelial MCF10A cells expressing either a shRNA silencing RB1 or a non-silencing control shRNA." (PMID 29915391, 2018). "Thus, we reasoned that the tumor samples without CtIP/RBBP8 expression might correlate with an altered expression of RB1." (PMID 24403251, 2013). "However, cytoplasmic RB1CC1 seems to play no role as a tumor suppressor activating the RB1 pathway." (PMID 20614030, 2010). "The selective suppression of tumor and transformed cells without significantly affecting their normal counterparts, coordinated by IFN-β and RB1, is an important surveillance and control mechanism against cancer." (PMID 37182173, 2023). "RB1, PRDM1, and TP63 expression was significantly downregulated in tumor samples with distant metastasis compared to tumor samples without metastasis, based on both TCGA and GSE30219 datasets." (PMID 38057344, 2023). "Alterations in IDH1, FGF19, RB1, and BAP1 appeared in patients with tumor size reduction, but not in those with non-responding tumors." (PMID 35311147, 2022). "The NAD+/NADH ratios and L-carnitine levels indicate that in the absence of RB1 and HK1, tumor cells can flexibly utilize alternate fuels such as glutamine or fatty acids to feed OXPHOS, fulfilling their bioenergetic demands." (PMID 36291051, 2022). "Of the single IHC results, RB1(N) was a predictor of poorer survival in the Taiwanese patients with OSCC, however, it was not independent of tumor stage." (PMID 33936170, 2021). "Seventy-six patient biopsies were grouped according to their tumor histological classification (CRPC or NEPC) and stratified into three categories based on RNA-seq values of MYCN expression (high vs. low) and RB1 genomic status (deletion, yes vs. no)." (PMID 34099734, 2021). "In the first and second experiments, there were no significant changes in the food intake or the tumor volume in the WEG, GE5, GE50 and Rb1 groups compared with those of each model group." (PMID 32020864, 2020). "There were no significant changes in the tumor-free body weights of the WEG, GE5, GE50 and Rb1 groups compared with those of each model group." (PMID 32020864, 2020).
tumor (continued). "WEG, GE5, GE50 and Rb1 did not improve the tumor-free weight of the mice, and GE5, GE50 and Rb1 did not improve the weight of the gastrocnemius muscle and epididymal fat in cancer cachexia mice." (PMID 32020864, 2020). "Its tumor suppressor function is mainly known due to the inhibition of the E2F1 transcription factor, which in the absence of RB1 pushes cells from G1 to S phase of the cell cycle." (PMID 31798638, 2019). "In the present study, we compared the expression of RB1 and FOXO1 between SCLs (tumor with monoallelic 13q14 deletion) and SFTs (that without 13q14 deletion), because the number of cases is sufficient for statistical analysis between these tumors." (PMID 28887603, 2018). "Our results on a series of germline, tumor DNAs and RNAs did not support any involvement of MED4 in the low penetrance phenotype, but confirmed the differentially methylated status of RB1 CpG85." (PMID 26925970, 2016). "This further suggested that there is no defect in the proliferation of tumor cells in LSL-Kras, Rb1∆L/∆L mice, and activation of oncogenic Kras can initiate senescence in these lesions similar to those in LSL-Kras, Rb1+/+ controls." (PMID 23936539, 2013). "In this study, we demonstrated that factors associated with poor outcomes in stage I and II nonsquamous NSCLC included nonadenocarcinoma, positive expression of p16INK4 and RB1 by IHC, and with CNV of CDKN2A gene in the tumor cells." (PMID 22619677, 2012). "RB1, ERBB2, and CCNE1 alterations were noted in patients who were not responsive to abemaciclib, suggesting that tumor biomarkers may help in the selection of patients who will respond to a rechallenge to a CDK4/6i." (PMID 36980743, 2023). "Since the tumor transcriptome findings also revealed high expression of glutamine pathway genes, we tested the ability of WERI-Rb1, Y79, and GL1-RB1 cells to use alternate fuels in the presence or absence of RB1 using the Seahorse mito-fuel flex assay." (PMID 36291051, 2022). "Interestingly, regardless of RB1 status, CDK4/6 inhibitors increase PD-L1 expression on tumor cells by decreasing its rate of degradation." (PMID 35911672, 2022). "The analysis did not detect MDM2 amplification, Rb1 deletion, break apart signals of EWSR1, FUS, DDIT3, or c-myc, or c-myc-IGH fusion signals, but it did detect more c-myc signals in 837 out of 996 tumor cells and 823 out of 1,000 tumor cells." (PMID 36514176, 2022). "Similarly, in non-MIBC, the RB1 under-expression has been related to non-response to immunotherapy with intravesical bacille Calmette-Guerin (BCG) and with tumor recurrence." (PMID 33194654, 2020). "However, 6 of 9 cores with strong RB1 staining demonstrated little to no YAP1 expression (see core SC8) and the vast majority of tumor cores were negative for RB1 and YAP1 staining, which mirrors our observations in SCLC cell lines." (PMID 29088741, 2017). "In the second tumor, the deleted region contained FOXO1 but not RB1." (PMID 28193293, 2017). "In addition, there was a near absence of reads for a portion of the RB1 gene (<10% of the reads compared with the normal liver and adenocarcinoma), in both resistant SCLC transformed tumours, but not in the resistant adenocarcinoma sample." (PMID 25758528, 2015). "In the MSK cohort, patients with FGFR2amp were enriched for MYC, RB1, and NMP1 alterations that were not noted on the G360 panel, which could be due to tumor heterogeneity or the low sample size of patients with FGFR2amp in the MSK cohort from a single institution." (PMID 38902956, 2024).
tumor (continued). "Gene expression changes between tumor with and without gene deletions were negative for MAP2K4 (fold change = −2.37, p = 0.0099), PTEN (fold change = −1.71, p = 0.10) and CDH1 (fold change = −1.59, p = 0.22), but close to one for RB1 (fold change = 1.08, p=0.62)." (PMID 26910888, 2016). "Also for tumor T7, from a non-familial unilateral patient, both high-level amplification of MYCN and RB1 inactivation was observed (20 nucleotides frameshift insertion in exon 1; NM_000321:c.25ins20:pT9fs), although RB1 inactivation was missed by WES because of low exon 1 coverage." (PMID 27126562, 2016).